RN7SL35P (RNA, 7SL, cytoplasmic 35, pseudogene)
Gene: Miscellaneous RNA gene on chromosome 7 (80,318,253 to 80,318,544, forward strand). Ensembl gene ENSG00000240347.
Homologues: Orthologues: chimpanzee Metazoa_SRP (90% identical), pig Metazoa_SRP (67% identical), guinea pig Metazoa_SRP (64% identical). Paralogues in human: RN7SL5P (71% identical), RN7SL2 (70% identical), RN7SL1 (69% identical), RN7SL3 (68% identical), RN7SL408P (68% identical), RN7SL4P (68% identical), RN7SL44P (68% identical), RN7SL517P (67% identical), RN7SL296P (67% identical), RN7SL480P (67% identical), RN7SL128P (67% identical), RN7SL650P (67% identical), and 700 more.